CD68 (CD68 molecule)
Description:
Could play a role in phagocytic activities of tissue macrophages, both in intracellular lysosomal metabolism and extracellular cell-cell and cell-pathogen interactions. Binds to tissue- and organ-specific lectins or selectins, allowing homing of macrophage subsets to particular sites. Rapid recirculation of CD68 from endosomes and lysosomes to the plasma membrane may allow macrophages to crawl over selectin-bearing substrates or other cells.
Synonyms: SCARD1; GP110; DKFZp686M18236; LAMP4
Tractability: Antibody: its Gene Ontology location is reachable by antibodies, with high confidence; UniProt places it where antibodies can reach, with medium confidence; UniProt predicts a signal peptide or a membrane-spanning region. PROTAC: its protein half-life has been measured.
Gene: Protein-coding gene on chromosome 17 (7,579,380 to 7,582,112, forward strand). Ensembl gene ENSG00000129226.
Subcellular location: Cell membrane (Isoform Short); Endosome membrane (Isoform Long); Lysosome membrane
Subcellular location (Human Protein Atlas): Golgi apparatus; Vesicles
Pathways (Reactome):
Immune System: Neutrophil degranulation
Gene Ontology:
Molecular function: protein binding
Biological process: cellular response to lipopolysaccharide; cellular response to nutrient levels; cellular response to oxidised low-density lipoprotein particle stimulus; establishment of protein localization to organelle; inflammatory response to antigenic stimulus; negative regulation of dendritic cell antigen processing and presentation; autocrine signaling
Cellular component: plasma membrane; azurophil granule membrane; late endosome membrane; lysosomal membrane; lysosome; membrane; cytoplasmic vesicle; endosome membrane
Genetic constraint (gnomAD): Loss-of-function variants: 24 observed, 33.33 expected, observed/expected ratio (o/e) 0.72, 90% interval 0.52 to 1.01. The upper end of that interval is the gene's LOEUF score, 1.01, which puts it in group 4 of 6, group 1 being the genes least tolerant of losing a copy. Missense variants: 461 observed, 467.78 expected, observed/expected ratio (o/e) 0.99, 90% interval 0.91 to 1.06. Synonymous variants: 190 observed, 189.26 expected, observed/expected ratio (o/e) 1, 90% interval 0.89 to 1.13.
Homologues: Orthologues: chimpanzee CD68 (99% identical), macaque CD68 (96% identical), pig CD68 (73% identical), rabbit CD68 (72% identical), guinea pig CD68 (67% identical), rat Cd68 (66% identical), dog CD68 (62% identical), zebrafish cd68 (22% identical), Drosophila melanogaster CG43668 (7% identical). Paralogues in human: LAMP1 (26% identical), LAMP2 (21% identical), LAMP5 (14% identical).
Diseases named in the same sentence as CD68 in open-access papers:
CD68 is named in the same sentence as 771 diseases in open-access papers, as found by Europe PMC text mining. Sharing a sentence is not in itself a finding about the gene and the disease. The quoted sentences say what the papers report.
breast carcinoma (190 papers, 2006 to 2025). "High-CD68(+)CD47(+) TAMs were an independent prognostic factor associated with shorter RFS among all breast cancers as well as among luminal type A invasive breast carcinomas." (PMID 40243442, 2025). "STAT1 expression in breast cancer was associated with poor prognosis and CD68-positive macrophage infiltration." (PMID 39843434, 2025). "Macrophages with CD68/CD163 double positivity are associated with poor prognosis of early-stage breast cancer, high-level histological grading, and high Ki67 expression." (PMID 41256322, 2025). "Alongside tumor growth restricting effects in the rat model of breast cancer, rat IgE 26 treatment was associated with significant recruitment of CD68 + macrophages into the tumor." (PMID 39934835, 2025). "Mahmoud et al38 found that higher numbers of CD68 macrophages were significantly associated with worse breast cancer‐specific survival and shorter disease‐free interval." (PMID 38151972, 2023). "We emphasized the importance of CD68+ cells in TLSs, which were present in about half of patients with locoregional recurrent breast cancer and were associated with improved PFS, especially in ER− patients." (PMID 38133211, 2023). "Higher amounts of CD68 + cells in breast cancer have been associated with a worse prognosis and M2 macrophages are known to stimulate cancer proliferation, angiogenesis and immunosuppression." (PMID 35917053, 2022). "Further staining for CD206 and CD68 was performed to observe the polarization of breast cancer-associated macrophages." (PMID 34659411, 2021). "In breast cancer, CD68 + tumor-associated macrophages are correlated with Ki67 expression in epithelial cells, suggesting that increased numbers of macrophages enhance tumor cell proliferation." (PMID 32731354, 2020). "In common, higher infiltration of TAMs, expressed both pan-macrophage marker CD68 and specific M2 markers, is associated with more aggressive molecular subtypes of breast cancer." (PMID 33194645, 2020). "In this study, CD68-labeled TAMs was significantly increased in breast cancer, and high macrophage infiltration was associated with advanced TNM stage, histological grade, LNM, ER status, PR status and recurrence." (PMID 31528120, 2019). "Both of the CD47 and CD68 expression were significantly higher in breast cancer tissues (P < 0.001), and associated with multiple clinicopathological parameters in breast cancer (P < 0.05)." (PMID 31528120, 2019). "Specifically, several studies using large cohorts of breast cancer patients have revealed that the expression of CD68 in tumor tissue is associated with higher grade, increased angiogenesis, and reduced disease-free survival." (PMID 29573739, 2018). "On examining 21 genes in RS, the CD68 is the only gene obviously associated with immune function in breast cancer." (PMID 29573739, 2018). "In short, our analyses show that high density of TAMs in breast cancer tissues, especially CD68+ TAMs in tumor stroma, is associated with worse prognosis in human breast cancer." (PMID 28427165, 2017). "As high cytotoxic T lymphocyte (CTL)/regulatory T cell (Treg) and high M1 (CD68+CD163-)/M2 macrophage ratios have been found to be associated with improved survival in breast cancer and cutaneous melanoma, respectively, we evaluated these ratios in our study." (PMID 28903377, 2017). "Immunohistochemistry was applied on the tumor tissues from 208 breast cancer patients to evaluate the local SAA-protein expression with additional CD68 stain to identify the tumor-associated macrophage (TAM) on the serial tissue sections." (PMID 27058895, 2016). "In the present study, we investigated the association between TAM marker, CD68, and Ras expression in breast cancer specimens." (PMID 25685069, 2015). "Our study was in accordance with the researches in bladder and breast cancer, suggesting that CD68 and CD163 are important diagnostic and prognostic factors in OSCC." (PMID 24883329, 2014).
breast carcinoma (continued). "While the presence of CD163+ macrophages in TS was more strongly associated with less favorable clinicopathological features, CD68+ macrophages in TS was a significant independent risk factor for a reduced breast cancer specific survival." (PMID 22824040, 2012). "Additionally, one other retrospective study of 76 patients in all breast cancer subtypes (23 TNBC cases) found improved rates of pCR with neoadjuvant chemotherapy (74.3% vs. 40%) were associated with high CD68 and PD-L1 expression using monoplex IHC43." (PMID 34732817, 2021). "Several clinical studies performed on Chinese cohorts of patients with breast cancer demonstrated the association of increased stromal infiltration of CD68+ macrophages with larger tumor size, higher histological grade, hormone receptor negativity in BC patients." (PMID 33194645, 2020). "CD68+ tumor-associated macrophages (TAMs) are pro-tumorigenic, pro-angiogenic and are associated with decreased survival rates in patients with cancer, including breast cancer." (PMID 29220404, 2017). "In this study, the CD68 antigen was used to identify the chemotaxis potential of adipose tissue to attract CD68-labelled macrophages, which may represent a risk for breast cancer and/or its unfavorable evolution." (PMID 26101731, 2015). "Increased CD68+ infiltration in breast cancer is associated with poorer outcome." (PMID 24961933, 2014). "Both High 2 and Basal groups had increased expression of macrophage inflammation markers CD68 and CD163, also associated with obesity, which correlates with poor prognosis in breast cancer." (PMID 40426890, 2025). "CD68 showed significantly higher expression levels in brain metastases compared to the corresponding primary breast cancers." (PMID 40510346, 2025). "Prior studies have shown that CD68+CD163+ macrophage infiltration, as well as CD68+CD163− macrophage presence in the TME, are associated with reduced overall survival in breast cancer patients." (PMID 40498004, 2025). "Previous studies on breast cancer use the anti-CD68 pan-macrophage marker, which has been shown to be mostly associated with unfavorable tumor stages and prognosis." (PMID 40498004, 2025). "Next, we compared the expression of 27 primary breast cancers and their paired brain metastases for CD68, CD163 and CD86." (PMID 40510346, 2025). "Luminal A breast cancer has significantly lower infiltration of CD68+ macrophages than luminal B, HER2+, and TNBC subtypes, with the latter three subtypes displaying relatively similar macrophage counts." (PMID 38426622, 2024). "CD163 has dethroned the earlier considered pan-macrophage marker CD68 as a better predictor for poor survival of breast cancer patients." (PMID 39451197, 2024). "Our results indicate that Cd68+Cd74+ApoE+ macrophages play a crucial role in breast cancer metastasis to the lungs." (PMID 39695088, 2024). "In the present study, we focused on the prognostic role of M2 TAMs (CD163+) and all TAMs (CD68+) in early breast cancer according to HER2 status and hormone receptor status." (PMID 38339385, 2024). "Clinical specimens of 59 breast cancer patients collected from the hospital also demonstrated that the median survival time in the high CD68+ macrophage infiltration group (1176 days) was lower than that in the low infiltration group (1740 days)." (PMID 38339428, 2024). "CD68 is known as a pan-macrophage marker and is correlated with a poor prognosis in breast cancer and lymphoma." (PMID 36693070, 2023). "Our study proposes potential predictors for the clinical prognosis of patients with locoregional recurrent breast cancer, emphasizing the prognostic value of immune cells within TLSs, especially CD68+ cells." (PMID 38133211, 2023). "For HER+ and ER−/HER2− recurrent breast cancers, TLSs were associated with longer PFS (p = 0.047), with the similar results for CD3+ cells (p = 0.023), CD38+ cells (p = 0.041), and CD68+ cells (p < 0.001) in TLSs." (PMID 38133211, 2023).
breast carcinoma (continued). "Apart from our finding of an expression correlation between CD155 and macrophages, CD155 related to CD68/CD163 was also observed in breast cancer tissues." (PMID 37441080, 2023). "We highlighted the importance of CD68+ cells within TLSs for PFS in locoregional recurrent breast cancer." (PMID 38133211, 2023). "We investigated the relationships between tumor expression of CD47 and CD68 macrophage content, subsets of tumor‐infiltrating lymphocytes (TILs), and vascular invasion in breast cancer." (PMID 36598153, 2023). "CD68+ cells in TLSs was a potential predictor for patients with locoregional recurrent breast cancer." (PMID 38133211, 2023). "Treatment with DNase I reduced the number of CD45+ and CD68+ cells in heart tissue from mice with breast cancer." (PMID 35309730, 2022). "Some studies reported CD163 and CD68 co-localization in macrophages, including in breast cancer, in agreement with our observations." (PMID 36230752, 2022). "We subjected 81 breast cancer specimens to immunostaining for CD68, CD163, PD-1, PD-L1, CD20, and pan-CK." (PMID 36362023, 2022). "In order to verify the findings from the database, we detected the protein level of NR1H3 and macrophage marker CD68 in paraffin tissue microarrays from breast cancer patients by IHC." (PMID 36699456, 2022). "The abundance of macrophages was assessed using the pan-macrophage marker CD68, and the results showed that CD68 expression correlated with EMT markers in breast cancer." (PMID 36611857, 2022). "There is also an increased incidence of CD68+ and CD163+ TAMs associated with breast cancer progression, including MAC387+ macrophages that are associated with viral infection." (PMID 35847899, 2022). "Number of CD68+ TAMs in tumor stroma were positively correlated with tumor size in breast cancer both in 144 patients from Sweden and in 60 patients from Egypt." (PMID 36686729, 2022). "We analyzed the spatial correlation of SET with the macrophage marker CD68 and the hypoxic zone marker hypoxia-inducible factor 1 subunit alpha (HIF1α) using published spatial transcriptome data from breast cancer patients." (PMID 36224346, 2022). "High amount of CD68+ and CD163+ TAMs was associated with lymph node metastasis, high Ki67 expression and poor prognosis in 1579 breast cancer patients from Zhejiang Provincial People’s Hospital and Zhejiang Tiantai People’s Hospital." (PMID 36686729, 2022). "Analysis of SEMA7A in normal breast tissue from biopsy by IHC.Kaplan–Meier analysis of SEMA7A, PDPN, and CD68 expression in >600 breast cancers, as well as ovarian, lung, and gastric cancer." (PMID 33649008, 2021). "The Kaplan-Meier survival curve showed that greater expression of S100A4 and CD68 was predictive of reduced relapse-free survival of patients with breast cancer, and of reduced overall survival of patients with ovarian or lung cancer after chemotherapy." (PMID 34145030, 2021). "In fact, macrophage CD68 is one of the genes in the standard Oncotype Dx score, a widely used prognostic tool used for patients with early-stage breast cancer." (PMID 34359704, 2021). "Increased PD-L1 expression and PD-L1 T-cells in postpartum patients.Observed co-expression of immune inhibitory PD-L1, PDPN, and CD68 in breast cancer TCGA patients." (PMID 33649008, 2021). "Onget al.62 also reported that rat mammary carcinoma had a significantly higher percentage of CD68+ macrophages as compared to benign mammary tumors with a lower growth rate." (PMID 34164110, 2021). "Gene chip analysis revealed that high CD68/CD8 ratio is also a predictive biomarker for reduced rate of pCR in 311 breast cancer patients from a Swedish cohort that underwent neoadjuvant chemotherapy (PTX and fluorouracil-doxorubicin-cyclophosphamide)." (PMID 33194645, 2020). "Further, 64% of CD68+ TAMs also expressed integrin β3 in breast cancer tissue as compared to 20% in normal breast tissue, indicating the potential to target these cells with αvβ3-NP-mediated drug delivery." (PMID 32685002, 2020).
breast carcinoma (continued). "In contrast to that study, this study found that VISTA was mainly expressed in CD68+ macrophages (mean = 32.58%) in breast cancer and in CD4+ T cells (mean = 4.97%), and lower levels of VISTA were found in CD8+ cytotoxic cells (mean = 4.48%)." (PMID 33250890, 2020). "We found that the percent of CD68+ macrophages was significantly increased in human breast cancer compared to normal tissue." (PMID 32685002, 2020). "In a retrospective study of 1,579 breast cancer specimens (Chinese cohort), high density of both CD68+ TAMs significantly correlated with lymph node metastasis." (PMID 33194645, 2020). "In our study, we observed that LOXL4 expression was positively correlated with EZH2 expression and macrophage infiltration, evidenced by CD68 staining in human breast cancer tissues." (PMID 32754259, 2020). "The fact that the TRIB3-AKT1 interaction prohibits the AKT1-FOXO1 interaction provides an opportunity to modulate the effects of the niche-enriched stress protein TRIB3, which indeed shows enhanced expression adjacent to CD68+ TAMs in breast cancer patients." (PMID 31844113, 2019). "We retrospectively reviewed the macrophage distribution in 1579 breast cancer specimens with anti-CD68 or anti-CD163 immunohistochemical staining, and further analyzed the overall survival data." (PMID 31528210, 2019). "Stromal LPA1 positivity (p = 0.017) and stromal LPA3 positivity (p = 0.004) were higher in breast cancer with adipose stroma containing CD68-positive crown-like structures (CLS)." (PMID 31035435, 2019). "High expression of CD68 protein was found in 157 cases (72.4%) of breast cancer patients, while in 15 cases (38.4%) of benign breast lesions." (PMID 31528120, 2019). "It suggested that CD68 was significantly increased in breast cancer tissues in comparison to benign breast lesions (χ2 = 18.532, P < 0.001)." (PMID 31528120, 2019). "In accordance with this, we found the frequent presence of CD68-labeled TAMs around or in the nest of breast cancer with high expression of CD47." (PMID 31528120, 2019). "In patients with breast cancer, a positive correlation of CCL2 with IL-1β and with macrophage marker CD68 in all breast cancer types was shown." (PMID 31921102, 2019). "Secondly, the prognostic significance of CD47 and CD68 in breast cancer was discussed only at histological level." (PMID 31528120, 2019). "We have previously reported infiltrating macrophages in adipose stroma of breast cancer recognized by CD68 and CD163 IHC, and the results of the previous study were used to analyze this relationship with the expression of ATX-LPA signaling-related proteins." (PMID 31035435, 2019). "In this study, we evaluated the expression and prognostic significance of CD47 and CD68-labeled TAMs in breast cancer solid tumors." (PMID 31528120, 2019). "In a recent study, Carvalho and colleagues demonstrated a bidirectional regulation of COX2 expression in canine mammary tumor cells and CD68 positive macrophages, assuming a tolerogenic tumor microenvironment." (PMID 31291992, 2019). "Using IHC staining on serial sections, Mor and colleagues demonstrated the presence of CD68+, aromatase-positive macrophages both around and within human breast cancers." (PMID 29898754, 2018). "Since macrophages are a known source of TGF-β1 in breast cancer, macrophages were detected by CD68 immunohistochemistry and positive cells were counted in BC lesion and nontumor tissues." (PMID 29581982, 2018). "Immunohistochemistry was performed to determine PD-L1 tumor cell expression and to enumerate CD8, CD4 and CD68 tumor-infiltrating leucocytes (TIL) in a cohort of 443 breast cancers categorized by molecular subtype." (PMID 28881675, 2017). "Prussian blue histology confirmed iron(III)+ HLM deposits at the edges of the invasive metastatic lesions, and immunofluorescence revealed these macrophages to be a sub-population of the CD68+ macrophages as in the other breast cancer tissues (p<0.0001)." (PMID 28898277, 2017).